IL31 (interleukin 31)
Diseases named in the same sentence as IL31 in open-access papers (continued):
Sharing a sentence is not in itself a finding about the gene and the disease.
lung fibrosis (continued). "Collectively, these observations make a compelling case that hematopoietic cell-derived IL-31 might play a role in the pathogenesis of pulmonary fibrosis by activating non-hematopoietic cells such as epithelial cells and mesenchymal cells." (PMID 33815402, 2021). "Regarding gp130 activation by IL-31, there is not much evidence of its relationship with ILDs, but one study in a mouse pulmonary fibrosis model found that IL-31 signals through STAT1 activation, and may constitute a possible pathway of mouse pulmonary fibrosis." (PMID 34207510, 2021).
urticaria (8 papers, 2017 to 2025). A vascular reaction of the skin characterized by erythema and wheal formation due to localized increase of vascular permeability. "Studies regarding IL-31 and urticaria were mainly concerning disease severity and therapy exploitations, as basophils have been found to produce pro-inflammatory cytokines (IL-4 and IL-13), after the interaction of IL-31/IL-31R." (PMID 35742951, 2022).
lymphoma (7 papers, 2017 to 2024). A malignant (clonal) proliferation of B- lymphocytes or T- lymphocytes which involves the lymph nodes, bone marrow and/or extranodal sites. "It is also known that lymphoma and inflammation associated itch is mediated by a Th2 cell-derived cytokine, interleukin (IL)-31 (IL-31), that directly interacts with its receptor IL-31RA located on TRPV1+/TRPA1+ sensory nerves in skin." (PMID 31488616, 2019). "Recent studies propose that the T-cell dysregulation associated with Hodgkin’s lymphoma contributes to high rates of pruritus associated with this malignancy and the cytokines IL-6, IL-8, and IL-31 may also play roles in lymphoma-associated or chronic itch." (PMID 28302100, 2017). "IL-31 was upregulated in mouse lymphoma, whereas its receptor Il31ra was persistently upregulated in Trpv1-expressing sensory neurons in mice with CTCL." (PMID 36520531, 2023). "Importantly in other lymphomas, such as follicular lymphoma, IL-31 promotes the growth of tumors in an autocrine and paracrine manner." (PMID 34948183, 2021). "Interleukin-31 (IL-31), T helper cell type 2- derived cytokine, activates a small subpopulation of primary sensory neurons expressing TRPV1, and TRPA1 through IL-31 receptor, and produced inflammatory and lymphoma-associated itch." (PMID 28515697, 2017). "In addition, we noticed a significant positive correlation between sIL-31 and the number of PB lymphoma cells, strengthening the hypothesis that IL-31 is produced by the malignant T cells." (PMID 34335777, 2021). "In this view, therapeutics that directly target IL-31 in CTCL could prove useful beyond the management of pruritus and help overcome disease-related immunosuppression to fire up anti-lymphoma cell-mediated responses." (PMID 38398754, 2024). "ELISA results showed low levels of IL-31 in nonmalignant skin tissue but a substantial increase in IL-31 levels in lymphoma tissues (P < 0.0001, vs. control)." (PMID 36520531, 2023).
alopecia (6 papers, 2013 to 2023). Hair loss usually from the scalp. "IL-31 is produced by activated T helper 2 cells and IL-31 transgenic animals showed skin lesions and alopecia." (PMID 24381786, 2013).
breast carcinoma (6 papers, 2015 to 2024). "This negative correlation is consistent with the observation that IL-31 inhibits the motility and activity of MDSCs in a model of breast carcinoma." (PMID 38391927, 2024). "Overall, our results demonstrate that IL-31 induces antitumor immunity by affecting various immune cells in a breast cancer model, highlighting the potential use of IL-31 as a therapeutic intervention." (PMID 32843492, 2020). "The growth rate of IL-31-expressing breast carcinomas is decreased in comparison with control tumors due, in part, to antitumor immunomodulation." (PMID 32843492, 2020). "Lastly, we evaluated the effect of IL31-IgG on metastasis in a clinically relevant breast carcinoma model." (PMID 28147314, 2017). "As with ovarian cancer, as well as with breast cancer, IL-31 might play a role in the metastasis and migration of tumoral cells." (PMID 35742951, 2022). "To further reinforce these findings, we demonstrated that in a murine breast carcinoma model, IL-31-expressing tumors contained significantly lower numbers of immunosuppressive cell populations such as CD4+CD25+ T cells, MDSCs and M2 macrophages, but not Tregs." (PMID 32843492, 2020). "However, the functional roles of IL-31/IL31RA signaling in basal-like breast cancer (BLBC) progression remain totally unclear." (PMID 32528891, 2020). "Here, we characterize the immunomodulatory effect of IL-31 in breast cancer." (PMID 32843492, 2020). "Since PyMT tumors that overexpress IL-31 exhibit an increase in IL-2 concentrations, we investigated whether there is a correlation between its expression and IL-31 or IL-31Ra in breast carcinoma biopsies from patients." (PMID 32843492, 2020). "In vivo breast carcinoma models including EMT6 and PyMT cell lines were used to analyze the effect of IL-31 on the composition of various immune cells in the tumor microenvironment using high-throughput flow cytometry." (PMID 32843492, 2020). "To create a model for investigating whether the immunomodulatory function of IL-31 affects tumor progression, we generated stable IL-31-expressing PyMT and EMT6 breast carcinoma cell lines (PyMT-IL-31 and EMT6-IL-31, respectively) using lentiviral transduction." (PMID 32843492, 2020).
COVID-19 (6 papers, 2021 to 2024). A disease caused by infection with severe acute respiratory syndrome coronavirus 2. "The ELF concentrations of IL-6, IL-8, IL-17A, IL-25, and IL-31 were significantly increased in COVID-19 patients." (PMID 38654351, 2024). "Furthermore, the 11th and 9th most differentially expressed transcripts in COVID-19 (+) biopsy belonged to IL31 and its receptor IL31RA, respectively." (PMID 38932146, 2024). "Compared with those in healthy volunteers, the concentrations of interleukin (IL)-6 (median 27.6 pmol/L), IL-8 (1045.1 pmol/L), IL-17A (0.8 pmol/L), IL-25 (1.5 pmol/L), and IL-31 (42.3 pmol/L) were significantly greater in the ELF of COVID-19 patients than in that of volunteers." (PMID 38654351, 2024). "Therefore, further research is needed to investigate the potential therapeutic targets for COVID-19 using IL-31/IL-33 axis modulation." (PMID 37240091, 2023). "On the other hand, reactivation of the signaling pathways involved in the decreased cytokines, such as IL-31, chemokines RANTES, MDC, PDGF, and TGF-β family members, might also be a novel strategy for COVID-19 therapy." (PMID 38476443, 2024). "The IL-31/IL-33 axis has emerged as a key player in the immune response against SARS-CoV-2, and further research is needed to fully understand its potential as a therapeutic target for COVID-19." (PMID 37240091, 2023).
dermatomyositis (6 papers, 2019 to 2026). Dermatomyositis (DM) is a type of idiopathic inflammatory myopathy characterized by evocative skin lesions and symmetrical proximal muscle weakness. "In a recent report, CB2 receptor expression was observed to be increased in dermatomyositis in certain cell types found in the skin, such as dendritic cells, B-cells, T-cells and macrophages, which produce IL-31, IL-4, interferon (IFN)-γ and IFN-β, compared to healthy skin." (PMID 36552866, 2022). "In vitro evidence of the action of a CB2 receptor agonist agent on peripheral blood mononuclear cells of patients with dermatomyositis (DM) demonstrate its ability to reduce the secretion of IL-31 (interleukin related to the innate and adaptive immune response in the skin)." (PMID 34133518, 2021). "Furthermore, lesional dermatomyositis skin contained significantly more IL-31-producing cells, of which CD4+ cells were the most abundant IL-31-expressing cell type." (PMID 31281316, 2019).
eczema (6 papers, 2012 to 2026). "The presence of single nucleotide polymorphisms in IL-31 in analyses combining data from three independent European study populations was linked to nonatopic, and not atopic, eczema." (PMID 22732598, 2012).
endometrial cancer (6 papers, 2016 to 2022). Primary or metastatic malignant neoplasm involving the endometrium (mucous membrane that lines the endometrial cavity). "Another study revealed the probable involvement of the same IL-31 polymorphism in endometrial-cancer susceptibility, thus representing a novel genetic marker." (PMID 35742951, 2022). "IL-31 and IL-33 were significantly accumulated in cancer patients (p < 0.001) and higher levels correlated with higher grade of endometrial cancer (p < 0.001) which shows that IL-31 and 33 are associated with a more severe or progressed disease." (PMID 34951691, 2022). "Recent studies showed that IL-31 and IL-33 protein levels were significantly elevated in sera from patients with endometrial cancer as compared to healthy controls." (PMID 30205617, 2018). "Because most patients received operation less than 18 months, the follow-up studies are still undertaken, and the correlation between IL-31/IL-33 and the overall survival time of the endometrial cancer patients is still under research." (PMID 27340318, 2016). "Patients with endometrial carcinoma displayed high serum levels of IL-31, which may represent promising disease biomarkers." (PMID 32528891, 2020). "Interestingly, the sensitivity and specificity of IL-31 and IL-33 expression and detection were higher than the typical endometrial cancer biomarkers CAE, CA-125, and CA19-9." (PMID 30205617, 2018). "Thus, in this very first study linking endometrial cancer with IL-31 and IL-33, these interleukins could serve as better biomarkers for endometrial cancer diagnosis and prognosis." (PMID 30205617, 2018). "IL-6, Il-11, IL-31, IL-33, TNF-α, TGF-β1, SDF-1 and CXCR are involved in endometrial cancer cell growth and metastasis or involved in epithelial mesenchymal transformation (EMT) or associated with advanced disease." (PMID 34951691, 2022).
uveitis (6 papers, 2015 to 2024). An inflammatory process affecting a part of or the entire uvea. "In patients with Behçet’s disease-associated uveitis, elevated serum levels of IL-33 and IL-31 have been reported, with IL-33 playing a role in the progression of experimental autoimmune uveitis (EAU)." (PMID 39519064, 2024). "But, although IL33 and IL31 are increased in serum of uveitis patients with Behçet’s disease and IL33 has been described to play a role in the course of EAU, the exact impact of the IL33/IL31 interplay on neutrophils in autoimmune uveitis is still unknown and merits further investigations." (PMID 36076947, 2022). "They found higher levels of IL-1β, IL-4, IL-17A, IL-17F, IL-21, IL-22, IL-31, IFN-γ, sCD40L, and TNF-α, with a significant difference for IL-17F, in BD-recurrent uveitis patients respect to the BD-remitted uveitis group, before drug infusion." (PMID 31134098, 2019). "Vitreous levels of these cytokines plus IL-31 were significantly higher in PDR than in ERM, MH or uveitis." (PMID 26352837, 2015). "Similar to the result of percent detectable, the vitreous levels of IFN-γ and sCD40L were significantly higher in uveitis group than in PDR group, whereas those of IL-4, IL-17A, IL-22, IL-31, and TNFα were significantly higher in PDR group compared with uveitis group." (PMID 26352837, 2015). "However, percent detectable of IL-10, IL-31, IFN-γ, sCD40L, and TNFα, and mean vitreous levels of IL-6, IL-10, IL-31, IFN-γ, sCD40L, and TNFα were significantly higher in eyes with uveitis than in those with ERM or MH (data not shown)." (PMID 26352837, 2015).
alopecia areata (5 papers, 2019 to 2025). Loss of scalp and body hair involving microscopically inflammatory patchy areas. "It found that people with alopecia areata had increased plasma levels of the Type 2 cytokines IL-33, IL-31 and IL-17E (IL-25), in addition to the Type 17 cytokines IL-17A, IL-21, IL-23 and IL-17F." (PMID 38892934, 2024). "However, although IL-31 and hair loss was described in mice it was not subsequently observed in patients with alopecia areata." (PMID 31281316, 2019).
atherosclerosis (5 papers, 2020 to 2025). A disease characterized by the build-up of fatty material and calcium deposition in the arterial wall resulting in partial or complete occlusion of the arterial lumen. "Treatments that target interleukins, such as IL-27, IL-28, IL-29, IL-31, IL-32, and IL-33, have shown promise in reducing fibrosis and inflammation, two important processes linked to the development of heart disorders such as atherosclerosis and heart failure." (PMID 39844544, 2025). "In the cardiovascular field, recent studies have shown that homocysteine-mediated miR-195-3p promotes the progression of atherosclerosis by targeting interleukin-31 (IL-31)." (PMID 41584300, 2025). "In summary, our results suggested that Hcy‐mediated miR‐195‐3p promotes macrophage inflammation and the progress of atherosclerosis by targeting IL‐31." (PMID 34592792, 2021). "Here, we demonstrated that elevated Hcy inhibits the expression of miR‐195‐3p, which in turn enhances IL‐31 expression and thereby causes the secretion of macrophages pro‐inflammatory factors IL‐1β, IL‐6 and TNF‐α and accelerate atherosclerosis." (PMID 34592792, 2021). "IL-31 may influence the inflammatory processes involved in atherosclerosis and hypertension by interacting with endothelial cells and vascular smooth muscle cells." (PMID 39844544, 2025).
periodontitis (5 papers, 2021 to 2026). An acute or chronic inflammatory process that affects the tissues that surround and support the teeth. "Moderate-to-severe AD was positively associated with the GCF levels of IL-31 and TSLP, whereas severe periodontitis was negatively associated with IL-31 (p < 0.05)." (PMID 37958576, 2023). "The combined effects of moderate-to-severe AD and severe periodontitis accounted for 16.5% of the variability in the GCF levels of IL-31, as determined by the corrected goodness-of-fit measure for linear models (Adj." (PMID 37958576, 2023). "This study was devoted to demonstrating the role of IL-31 and IL-34 in the diagnosis and treatment of chronic periodontitis (CP)." (PMID 36879647, 2023). "In the paper that compared cytokine levels for 54 periodontitis patients and 40 healthy controls, cytokines IL‐1β, IL‐4, IL‐6, IL‐10, IL‐17A, IL‐17F, IL‐21, IL‐22, IL‐23, IL‐25, IL‐31, IL‐33, IFN‐γ, sCD40L and TNF‐α were measured in saliva and serum at baseline, 3, 6 and 12 months after treatment." (PMID 41580300, 2026). "Finally, a two-way analysis of variance (ANOVA) was performed on a sample of 58 patients to explore further the effects of moderate-to-severe AD diagnosis and severe periodontitis on the GCF levels of IL-31." (PMID 37958576, 2023). "The expression of IL-31 and IL-34 in the gingival tissue of patients with severe periodontitis was significantly higher than that of patients with mild periodontitis, indicating that IL-31 and IL-34 may be closely related to the severity of periodontitis." (PMID 36879647, 2023). "Therefore, it is plausible that the GCF levels of IL-31 in periodontal tissues depended on the mast cell count relative to the severity of periodontitis." (PMID 37958576, 2023). "On the other hand, severe periodontitis can also negatively affect the levels of IL-31 in the GCF." (PMID 37958576, 2023). "In addition, we also showed that AD and periodontitis influence IL-31 in opposing and independent ways, while TSLP levels are only influenced by AD diagnosis." (PMID 37958576, 2023). "Consequently, enhanced levels of IL-31 overpass into the periodontal tissues from the systemic circulation, a process which may be further facilitated by the vascular changes inherent to periodontitis." (PMID 37958576, 2023). "A multiple regression analysis was performed to evaluate the impact of AD diagnosis and the covariates age, gender, smoking status, and periodontitis severity on the GCF levels of IL-13, IL-31, and TSLP." (PMID 37958576, 2023). "In conclusion, the principal findings of this study indicate that both AD and severe periodontitis independently and opposingly affect the GCF levels of IL-31." (PMID 37958576, 2023). "Regarding intestinal tissue analyses, higher levels of IL-1β, IL-4, IL-6, IL-17A, IL17F, IL-21, IL-31, IL-33 and sCD40L were found in patients with IBD and periodontitis." (PMID 34501547, 2021). "Regarding intestinal tissue analyses, higher levels of IL-1β, IL-4, IL-6, IL-17A, IL17F, IL-21, IL-31, IL-33 and soluble CD40 ligand (sCD40L) were found in patients having IBD activity and periodontitis." (PMID 34501547, 2021). "Briefly, moderate-to-severe AD patients consistently presented higher GCF levels of IL-31 than healthy controls, regardless of periodontal status and periodontitis severity." (PMID 37958576, 2023). "In contrast, a significant negative association was found between severe periodontitis diagnosis and the GCF levels of IL-31 (p < 0.05)." (PMID 37958576, 2023). "Therefore, this study aims to compare the GCF levels of IL-13, IL-31, and TSLP between AD patients and healthy controls and to explore the impact of periodontitis and AD on the GCF levels of these molecules." (PMID 37958576, 2023). "Mean levels of GCF IL-31 in AD patients with no/mild, moderate, and severe periodontitis were 153.273 ± 3.424, 153.233 ± 6.873, and 146.951 ± 7.931 pg/mL, respectively." (PMID 37958576, 2023).
periodontitis (continued). "Clinical evidence shows higher levels of IL-31 in both the GCF and saliva of periodontitis patients compared to their healthy counterparts and that those levels were seen to decrease after periodontal treatment, implying a potential role of IL-31 in the pathogenesis of periodontitis." (PMID 37958576, 2023).
contact dermatitis (4 papers, 2018 to 2025). An inflammatory skin condition caused by direct contact between the skin and either an irritating substance or an allergen. "On the other hand, the role of IL-31 in the development of contact dermatitis/contact hypersensitivity (CHS) is not well understood." (PMID 29703903, 2018). "However, the role of IL-31 in development of contact dermatitis/contact hypersensitivity (CHS), which is mediated by hapten-specific T cells, including Th2 cells, is not fully understood." (PMID 29703903, 2018). "Furthermore, psoriasiform eruptions and contact dermatitis may result from the suppression of Th2 cytokines due to IL-31 inhibition, which can lead to the compensatory activation of Th1 and Th17 pathways." (PMID 40364058, 2025).
follicular lymphoma (4 papers, 2017 to 2021). Follicular lymphoma is a form of non-Hodgkin lymphoma characterized by a proliferation of B cells whose nodular structure of follicular architecture is preserved. "The elevation of IL-31/IL31RA signaling was indicated to be responsible for primary follicular lymphoma cell proliferation." (PMID 32528891, 2020). "We have previously demonstrated that IL-31 is expressed on the surface membrane and in the cytoplasm of normal and Follicular Lymphoma B cells." (PMID 29156718, 2017). "In addition, IL31 is highly expressed in hematological malignancies such as follicular lymphoma, germinal cancer derived B-cell malignancy, and T cell lymphoma, and was found to contribute to tumor growth via the STAT1/STAT3 signaling pathway." (PMID 28147314, 2017). "The expression of IL-31 and IL31RA was found to be higher in lymph nodes from follicular lymphoma patients with grade IIIa compared with grade I/II." (PMID 32528891, 2020). "In this respect, we have previously demonstrated that IL-31 is not released in soluble form by Follicular Lymphoma B cells, but shed in microvesicles that serve as intercellular messengers." (PMID 29156718, 2017).
lung carcinoma (4 papers, 2021 to 2024). "Since IL-31 has been studied for the first time in epithelial cells, the first tumor of interest was lung cancer." (PMID 35742951, 2022).